SESN2 (sestrin 2)
Diseases named in the same sentence as SESN2 in open-access papers (continued):
Sharing a sentence is not in itself a finding about the gene and the disease.
Sepsis (continued). "Sesn2 protein exerted a protective effect against CLP-induced mortality, and inversely knockout of Sesn2 exacerbated mortality, particularly at the early stage of sepsis." (PMID 34482365, 2021). "SESN2−/− mice exhibited a marked increase in DC pyroptosis at 24 h after sepsis, which was reversed by pretreatment with salubrinal." (PMID 34741186, 2021). "To explore the potential role of SESN2 in the development of sepsis in vivo, we observed the survival rates of WT and SESN2−/− mice after CLP." (PMID 34741186, 2021). "In summary, we propose that SESN2 impedes NLRP3–ASC–CASP-1-mediated pyroptosis by preserving ER homeostasis during sepsis." (PMID 34741186, 2021). "To evaluate the impact of SESN2 in sepsis and the molecular mechanism, we further examined the 7-day survival rates of mice subjected to CLP and pretreated with or without salubrinal." (PMID 34741186, 2021). "DCs in Sesn2−/− mice were morphologically altered in the context of sepsis, and it was characterized by cytoplasmic dilatation, mitochondrial membrane incrassation, and mitochondrial cristae disorder." (PMID 34482365, 2021). "Sepsis induced a decrease in the number of CD11c+ splenic cells, while SESN2−/− mice showed a significantly fewer CD11c+ splenic cells than WT mice at 24 h after CLP." (PMID 34741186, 2021). "The colocalization of the NLRP3 and ASC proteins was higher in the sepsis group than in the sham group and was markedly increased in the SESN2−/− septic mice compared to WT septic mice." (PMID 34741186, 2021). "Overall, these results revealed that SESN2 suppresses CHOP-mediated activation of NLRP3/CASP-1-dependent pyroptosis during sepsis." (PMID 34741186, 2021). "And study has found that increasing the expression of SESN2 to promote mitophagy can protect the host from sepsis." (PMID 34594329, 2021). "To test the effect of SESN2 on the inflammatory response in the context of sepsis, we measured the levels of inflammatory cytokines in both WT and SESN2−/− mice." (PMID 34741186, 2021). "A recent study reported that SESN2 suppressed sepsis by inhibiting NLRP3 activation and inducing autophagy in macrophages." (PMID 32155890, 2020). "In the cecal ligation and puncture (CLP) mouse sepsis model and endotoxemia-induced sepsis model, SESN2 levels were increased, and the more severe the sepsis, the higher the expression of SESN2 and vice versa." (PMID 31867002, 2019). "This study highlighted the protective effect of SESN2 from sepsis and sepsis shock by maintaining mitophagy activation to inhibit NLRP3 inflammasome hyperactivation for immunological homeostasis." (PMID 31867002, 2019). "Further supporting the immunosuppressive role of mitophagy in sepsis, a recent study showed that senstrin 2 (SESN2) restrains NLRP3 activity by promoting the elimination of damaged mitochondria in macrophages." (PMID 29951054, 2018). "Additionally, SESN2 suppresses DC ferroptosis in sepsis by downregulating the ATF4-CHOP-CHAC1 signaling pathway, suggesting antioxidative potential." (PMID 38348451, 2024). "Studies have shown that the knockout of Sesn2 can induce endothelial dysfunction through AMPK dependent pathway and accelerate the formation of LPS induced-myocardial fibrosis, while the over-expression of Sesn2 can activate AMPK to alleviate sepsis induced-myocardial dysfunction." (PMID 37063954, 2023). "However, the potential effects of SESN2 in regulating dendritic cells (DCs) pyroptosis in the context of sepsis and the related mechanisms are poorly characterized." (PMID 34741186, 2021). "In addition, decreased pro‐inflammatory cytokine expression and inflammatory cell infiltration were observed in hippocampi of AAV2‐SESN2‐injected mice with SAE, consistent with the anti‐inflammatory role of SESN2 in sepsis." (PMID 32363721, 2020). "We proposed that SESN2 might be one of the favorable factors in immune regulation of DCs under ERS in the setting of sepsis." (PMID 32071292, 2020).
Sepsis (continued). "SESN2 was also significantly up‐regulated in skin tissue and sepsis." (PMID 32363721, 2020). "Notably, NO, generated by nitric oxide synthase 2, upregulates SESN2 protein levels contributing to inflammasome suppression during LPS-induced sepsis." (PMID 29951054, 2018). "Therefore, SESN2 has multiple regulatory effects and could be a promising therapeutic target and play a protective role in various inflammatory diseases, such as sepsis." (PMID 38020710, 2023). "Considering that Sesn2 can profoundly affect the pathological process of ferroptosis via antioxidation, we hypothesize that Sesn2 might be critically involved in the immunomodulation of DCs to protect against ferroptosis resulting from sepsis." (PMID 34482365, 2021). "In the late stage of sepsis, macrophages will release high mobility group protein B1 (HMGB1), which can stimulate the expression of Sesn2 in DCs." (PMID 35619718, 2022). "Second, the potential effects of SESN2 and ATF4 double knockdown in sepsis models need to be further tested." (PMID 34741186, 2021). "The expression of SESN2 significantly increases in response to ERS, which is triggered by both specific stimuli and sepsis." (PMID 34741186, 2021). "Our previous report verified that SESN2 alleviates excessive inflammation and dysfunction of DCs by interacting with ATF4 to decrease the extent of ERS during sepsis." (PMID 34741186, 2021). "The present study aimed to verify the protective effects of SESN2 on apoptosis of DCs under stimulation with HMGB1 and during sepsis and tried to identify the key molecules in ERS-related apoptosis signaling pathways." (PMID 32071292, 2020). "Sepsis mortality rates were markedly higher for SESN2−/− mice then for WT mice, while treatment with salubrinal (2 mg/kg) 1 h prior to CLP provided significant protection against CLP-induced mortality in both WT and SESN2−/− mice." (PMID 34741186, 2021). "Sestrin 2 induces mitophagy to clean damaged mitochondria and inhibit NLRP3 activation in sepsis." (PMID 33324236, 2020). "Furthermore, the study discovered that Sestrin2 (SESN2) effectively suppressed excessive activation of the NLRP3 inflammasome and the resulting caspase-1-dependent pyroptosis, leading to an enhanced prognosis in sepsis." (PMID 38816685, 2024). "However, we noticed that the noncanonical CASP-11 pathway is activated during sepsis, but we did not valuate the possible role of SESN2 in this noncanonical pathway, which is worth investigating in further study." (PMID 34741186, 2021). "Salubrinal significantly reduced the mortality rate of SESN2−/− mice but not that of WT mice, which confirmed that SESN2 plays a protective role in sepsis by alleviating ERS." (PMID 34741186, 2021).
lung carcinoma (19 papers, 2012 to 2025). "The positive feedback loop between sestrin 2 and mTORC2 is vital for lung cancer cell survival during glutamine deficiency." (PMID 34784907, 2021). "In non‐small cell lung cancer, high expression of SESN2 was associated with prolonged overall survival compared with that of patients with low SESN2 expression." (PMID 33942488, 2021). "Among tissue specimens resected from 77 lung cancer patients, only one was detected with point mutations in Sesn2 gene." (PMID 25962159, 2015). "Importantly, supply of miR-182-5p-mimicking molecules significantly suppressed the expression of SESN2 and was associated with longer survival of glioma or lung cancer patients." (PMID 31546746, 2019). "Furthermore, high expression of miR-182-5p and low expression of SESN2 mRNA tend to be associated with longer survival of glioma or lung cancer patients using public available gene expression datasets and online tools for prediction of clinical outcomes." (PMID 29662624, 2018). "Mutations of Sesn2 gene identified from 77 Chinese lung cancer patients." (PMID 25962159, 2015). "Consistent with reports from colorectal and lung cancers, our results revealed that SESN2 expression was significantly reduced in prostate cancer tissues and cell lines." (PMID 40661871, 2025). "A recent study in A549 cells suggests that SESN1 and SESN2 regulate aberrant STAT3 activation in lung cancer, limiting malignant proliferation and enhancing sensitivity to apoptosis." (PMID 40361504, 2025). "SESN1 and SESN2 frequently exhibit reduced expression in lung tumours, with decreased SESN2 levels marking a poor prognosis for lung cancer patients." (PMID 40361504, 2025). "Knockdown of SESN2 in lung cancer cells decreases both cancer cell survival and migration, while leading to overproduction of ROS by blocking the oxidative stress response." (PMID 38534454, 2024). "The metabolic reprograming that implicates SESN2, mTORC1 and mTORC2, enables lung cancer cells survival under glutamate deprivation conditions." (PMID 37284849, 2023). "This work demonstrates that SESN2 regulates mTORC1 and mTORC2 in different ways, finally leading to redox balance and lung cancer cells survival under glutamine-depleted conditions." (PMID 37284849, 2023). "In colorectal, hepatocellular and lung cancer, SESN2 is characterized as a tumor suppressor because of its decreased expression, which is associated with advanced tumor stage, metastasis and poor survival of cancer patients." (PMID 36611970, 2022). "In osteosarcoma and lung cancer, the inhibition of SESN2 expression enhanced the cytotoxic effects of chemotherapeutic drugs." (PMID 36611970, 2022). "The depletion of glutamine resulted in the binding of sestrin 2 to mTORC2 to increase the stability of the sestrin 2 protein and reduce the activity of mTORC1, thus, preventing lung cancer cell death." (PMID 34784907, 2021). "Lung cancer patients with a high expression of sestrin 2 had a longer overall survival rate than those with low expression of this protein." (PMID 34784907, 2021). "In A549 lung cancer cells, sestrin 2 knockdown decreased the mRNA expression of ATP-binding cassette transporter ABCG and ABCA2 (drug resistance marker genes) and increased sensitivity to doxorubicin." (PMID 34784907, 2021). "It appeared that the analytic results using PROGmiR and PRECOG partially agreed our findings because high expression of miR-182-5p and low expression of SESN2 contributed to longer survivals in glioma and lung cancers." (PMID 29662624, 2018). "For SESN2 gene, the low expression of SESN2 showed significantly longer survival in both glioma and lung cancer." (PMID 29662624, 2018).
lung carcinoma (continued). "In summary, of the 77 lung cancer patients examined, 57 patients were scored with low and medium expression of Sesn2, 20 patients were scored with high expression of Sesn2." (PMID 25962159, 2015). "The clinical relevance of Sesn2 expression level was evaluated in lung cancer tissue specimens resected from 77 lung cancer patients." (PMID 25962159, 2015). "SESN2 was significantly upregulated in multiple glutamine-deprived lung cancer cell lines." (PMID 40361504, 2025). "The up-regulation of SESN2 may inhibit the growth of lung cancer cells and slow down the progression of tumors by affecting the cell cycle and cell proliferation." (PMID 39275122, 2024). "Additionally, SESN2 knockdown attenuated the proliferation and migration of lung cancer cells as well as enhancing the cytotoxic effects of ROS-inducing chemotherapeutic drugs (doxorubicin and cisplatin)." (PMID 36611970, 2022). "Furthermore, these authors showed that overexpressed sestrin 2 was a marker for poor prognosis in lung cancer by analyzing the PrognoScan database and Kaplan–Meier Plotter." (PMID 34784907, 2021). "Sestrin 2 also has a potentially oncogenic function in lung cancer." (PMID 34784907, 2021). "Next, we determined the protein levels of Sesn2 in those lung cancer tissues by immuno-blotting." (PMID 25962159, 2015). "Surprisingly, in contrast to most tumor suppressors generally down-regulated in cancer tissues, we have observed a significant portion of high expression of Sesn2 (20 out of 77) in the examined lung cancer patients, their Sesn2 levels even are much higher than their adjacent normal lung tissues." (PMID 25962159, 2015). "Though the Sesn2 protein levels vary a lot in the examined lung tissues, there is a clear positive correlation between the low Sesn2 expression level and a poor survival rate in the examined lung cancer patients." (PMID 25962159, 2015). "The very low mutation rate of Sesn2 gene in human lung cancer suggests the structural alteration of Sesn2 gene is not a major cause contributed to the malignant transformation of lung epithelial cells." (PMID 25962159, 2015). "We validated Sesn2 as the candidate of lung cancer tumor suppressor." (PMID 25962159, 2015). "The expression level of Sesn2 may serve as a prognostic marker for Chinese lung cancer patients in the clinic." (PMID 25962159, 2015). "To study the potential impact of the SESN1 and SESN2 genes in lung carcinogenesis, we analyzed mRNA expression of these genes using The Cancer Profiling Expression Array (Clontech) containing equal amounts of mRNA from matched human lung cancers and normal tissues from the same patient." (PMID 31857853, 2019). "Our current data indicate that the expression levels of the SESN1 and/or SESN2 genes are often diminished in human lung cancers and suppression of SESN1/2 may support tumor growth and/or progression through such mechanisms as stimulation of cell growth, proliferation, mutagenesis, and angiogenesis." (PMID 31857853, 2019). "Therefore, we conclude the low expression level of Sesn2 associates with a poor survival rate in Chinese lung cancer patients, and the expression level of Sesn2 may serve as a potential prognostic marker for lung cancer patients in the clinic." (PMID 25962159, 2015).
lung carcinoma (continued). "The anti-cancer functions of sestrin 2 are closely related to the inhibition of mTORC1 activity in endometrial cancer, CRC, and lung cancer." (PMID 34784907, 2021). "We also observed the same trend in radiated A549 lung cancer cells, where IR-induced AMPK activity and expression was prevented with SESN2 siRNA." (PMID 22363791, 2012). "A study on lung cancer in a mouse model showed that knockout of either Sesn1, Sesn2, or both does not impact tumour formation." (PMID 40361504, 2025). "In previous studies, the down-regulation of SESN2 was shown to accelerate both colitis and colon carcinogenesis, while SESN1 and SESN3 were found to be strongly down-regulated in various types of cancer tissues, such as lung cancers and lymphomas." (PMID 35195231, 2022). "Therefore, we conducted studies based on a mouse lung cancer model and human lung adenocarcinoma A549 cells to evaluate the potential impact of SESN1 and SESN2 on lung carcinogenesis." (PMID 31857853, 2019). "To examine if over-expression of miR-182-5p could also regulate SESN2 and TP53INP1 in different cell type, we introduced a tetracycline-inducible (tet-on) miR-182-5p expression system to H1299 lung cancer cells to express miR-182-5p." (PMID 29662624, 2018). "Additionally, numerous lung cancer expression datasets indicate a negative correlation between SESN2 expression and patient survival." (PMID 38534454, 2024). "Interestingly, some reports have suggested that sestrin 2 expression can be elevated in some cancers, such as the non-small cell lung cancer (NSCLC) line A549, and that its expression is negatively correlated with lung cancer patient survival." (PMID 33673488, 2021). "Thus, Sesn2 expression levels are not likely affected by these clinicopathological features of lung cancer patients." (PMID 25962159, 2015).